EZH2 (enhancer of zeste 2 polycomb repressive complex 2 subunit)
Diseases named in the same sentence as EZH2 in open-access papers (continued):
Sharing a sentence is not in itself a finding about the gene and the disease.
breast cancer (continued). "There was an obvious difference in allele frequency (χ2 =8.286, P=0.004) and genotype frequency (χ2 =8.972, P=0.003) of EZH2 rs6464926, and T allele could increase the susceptibility to breast cancer (OR =1.240, 95% CI: 1.071–1.435, P=0.004)." (PMID 29089464, 2018). "Though downregulation and loss-of-function mutations suggest tumor suppressive activity of EZH2 in some cancers, evidence to demonstrate that EZH2 with gain-of-function mutations act as oncogene in numerous others, such as prostate cancer, breast cancer and BC37." (PMID 29445179, 2018). "Moreover, the findings provide preliminary evidence suggesting potential of high level of EZH2 expression as a prognostic marker in smoking-associated breast cancer." (PMID 29396474, 2018). "Whereas cohorts of virgin females bearing the wild-type or one conditional allele of Ezh2 developed measurable mammary tumours after an average onset of 67 and 61 days, respectively, Ezh2-deficient mice displayed a significant delay in tumour onset to an average of 145 days." (PMID 29959321, 2018). "Our findings suggest that EZH2 rs12670401 and EZH2 rs6464926 polymorphisms may be significantly correlated with breast cancer susceptibility and prognosis." (PMID 29089464, 2018). "Our study also found that the combined genotype of EZH2 rs12670401 (TC + CC) and EZH2 rs6464926 (CT + TT) could result in an obvious increase in the susceptibility to breast cancer, indicating that there may be interactions between the two loci." (PMID 29089464, 2018). "Using EZH2 mutants with a deletion in the nuclear localization signal and a T367 phosphorylation deficient mutant, we directly demonstrate that cytoplasmic localization and T367 phosphorylation are sufficient for EZH2-mediated breast cancer progression." (PMID 30022044, 2018). "To summarize, our study provided strong evidence that EZH2 rs12670401 and rs6464926 polymorphisms may be correlated with breast cancer susceptibility and prognosis." (PMID 29089464, 2018). "EZH2 expression is reportedly associated with aggressive prostate cancer, esophageal cancer, and breast cancer, whereas its clinical importance in HNSCC is yet unknown." (PMID 30469511, 2018). "EZH2 is upregulated in breast carcinoma cells and is associated with aggressiveness of the disease." (PMID 29396474, 2018). "When performing cross-classification of samples using EZH2 and ER expression, women with ER expression below the median in normal epithelium and concomitant EZH2 expression above the median displayed even higher risk of breast cancer than if only using EZH2 for classification." (PMID 28253895, 2017). "Women with a breast biopsy in which more than 20% of normal epithelial cells expressed EZH2 had a significantly increased risk of developing breast cancer (odds ratio (OR) 2.95, 95% confidence interval (CI) 1.11–7.84) compared to women with less than 10% EZH2 epithelial expression." (PMID 28253895, 2017). "Additionally, women with high EZH2 expression and low estrogen receptor (ER) expression had a 4-fold higher risk of breast cancer compared to women with low EZH2 and low ER expression (OR 4.02, 95% CI 1.29–12.59)." (PMID 28253895, 2017). "However, studies addressing the clinical relevance of EZH2 expression in benign breast disease and normal breast tissue as a biomarker of breast cancer risk have been limited by small sample sizes." (PMID 28253895, 2017).
breast cancer (continued). "Furthermore, this regulation suppressed EZH2 oncogenic functions and EZH2 enzymatic activity (trimethylation of H3K27) is inversely associated with GSK3β activity in tumor tissues from human breast cancer patients." (PMID 27494834, 2016). "Furthermore, EZH2 is upregulated in breast cancer, and high EZH2 levels are associated with aggressive breast cancer." (PMID 26349457, 2016). "The developmental regulator EZH2 functions through regulation of DNA methylation, and has been implicated in B-cell lymphomas through somatic mutations, promotion of transformation in breast cancer, as well as progression in prostate cancer." (PMID 27145341, 2016). "In fact, Ezh2 overexpression or gain of function mutations are known to be associated with several aggressive human solid tumour types, including prostate cancer, breast cancer, and different types of lymphomas, and are indicators of poor prognosis in patients." (PMID 26993608, 2016). "Moreover, the CpG sites methylated in breast cancer overlapped with DNase I hypersensitive sites associated with open chromatin and active transcription as well as with regions bound by EZH2 in HMECs." (PMID 26923702, 2016). "Furthermore, immunohistochemistry further suggested that FOXO3 expression was significantly associated with BRCA1 status in EZH2-positive breast cancer." (PMID 27043660, 2016). "Recently, it has been confirmed that a cyclopentenyl analog of 3-deazaadenosine, 3-deazaneplanocin A (DZNep), can reduce EZH2 expression in breast cancer cells and cause concomitant inhibition of H3K27me3 expression, which causes derepression of epigenetically silenced target genes." (PMID 27223261, 2016). "High expression of EZH2 was found to be associated with mammary carcinoma malignancy." (PMID 27502594, 2016). "In addition, the immunohistochemical expression level of EZH2 was associated with the degree of malignancy in canine mammary carcinoma." (PMID 27502594, 2016). "In addition, we found that while high EZH2 expression is overall correlated to a poor prognosis in breast cancer, this association can be subdivided into two opposite components." (PMID 26637281, 2015). "Moreover, an imbalance in H3K27 methylation owing to overexpression of EZH2 has been implicated in metastatic prostate and aggressive breast cancers, in which a highly significant overlap between PRC2- and H3K27me3-occupied genes was observed." (PMID 24093096, 2013). "EZH2 has been implicated in regulating invasion of breast cancer cells." (PMID 24294976, 2013). "EZH2 expression was linked to an increased risk for breast cancer development in females, suggesting that EZH2 detection could have diagnostic value for this cancer form." (PMID 20920340, 2010). "Moreover, an imbalance of H3K27 methylation owing to overexpression of EZH2 has been implicated in metastatic prostate and aggressive breast cancers, in which a highly significant overlap between PRC2- and H3K27me3-occupied genes was observed." (PMID 20028503, 2009). "This would indicate that EZH2 constitutes a therapeutic target for BRCA1-deficient breast cancer." (PMID 19709408, 2009). "Moreover, the knock-down experiments show that BRCA1-deficient mammary tumor cells are dependent on EZH2 for their survival." (PMID 19709408, 2009). "We indeed found that BRCA1-deficient mouse mammary tumors have higher EZH2 protein levels than control tumors, also indicated by the higher percentage of tumor cells with EZH2 expression above background (77% in KB1P tumors versus 11.5% in KP tumors; Wilcoxon P < 0.029)." (PMID 19709408, 2009). "Our findings suggest that Polycomb protein EZH2-mediated H3K27me3 might be the key chromatin mark associated with the transcriptional repression of CDKN1C in breast cancer cells." (PMID 19340297, 2009). "Finally, we show that the downregulation of CDKN1C by EZH2 in breast cancer is associated with a poor disease outcome." (PMID 19340297, 2009).
breast cancer (continued). "In the study presented here, we set out to determine whether increased EZH2 expression also characterizes human BRCA1-deficient breast cancer, and whether BRCA1-deficient tumor cells are dependent on high EZH2 levels for their survival." (PMID 19709408, 2009). "Recently, enhancer of zeste homologue 2 (EZH2), a member of the PcG protein family, has been linked to the aggressiveness of human cancers, including lymphomas, breast cancer and prostate cancer." (PMID 15856046, 2005). "Since its overexpression has been described in BRCA1-deficient mouse mammary tumors, researchers investigated whether EZH2 was essential for cancer cell survival or a tumorigenic byproduct, demonstrating an EZH2-dependence, while BRCA1-intact cells tolerate EZH2 loss." (PMID 40136510, 2025). "However, it remains unclear whether specific genetic variants of EZH2 are associated with breast cancer risk." (PMID 39744000, 2024). "The role of EZH2 in carcinogenesis has been extensively documented in numerous studies showing that EZH2 upregulation, or gain-of-function mutation, is often correlated with an adverse prognosis in various cancer types, including melanoma, prostate cancer, breast cancer, and others." (PMID 38275371, 2023). "Furthermore, EZH2 was found to be associated with aggressiveness of prostate and breast cancer." (PMID 36428492, 2022). "Thus, we suggest that targeting EZH2 in ARID1A-mutated breast cancer could be a valid therapeutic option to explore." (PMID 33741974, 2021). "Therefore, to evaluate the association of identified EZH2 target genes with breast cancer, we investigated their expression in various cancerous cell lines including non-cancerous as well as primary breast tumors and normal breast tissues in MERAV expression database." (PMID 30760814, 2019). "In the case and control groups, there were significant differences in the allele frequency (χ2 =9.356, P=0.002) and genotype frequency (χ2 =12.22, P<0.001) of EZH2 rs12670401, and C allele could increase the susceptibility to breast cancer (OR =1.255, 95% CI: 1.085–1.452, P=0.002)." (PMID 29089464, 2018). "However, if this locus is perturbed, as is seen in many breast cancers, then loss of Ezh2 might have quite different consequences." (PMID 30080881, 2018). "However, the presence of high EZH2 levels in association with low H3K27me3 in aggressive breast cancers suggests that EZH2 operates via a currently unknown H3K27me3-independent mechanism." (PMID 30022044, 2018). "Furthermore, the samples from never-smoked patients harbor low level of EZH2 irrespective of ductal or lobular type of cancer tissue in comparison to smoking-associated breast cancer tissue samples, which minimizes the role of inter-tumoral heterogeneity in EZH2 expression level." (PMID 29396474, 2018). "We hypothesized that in the cytoplasm, pEZH2(T367) may regulate the migratory and invasive abilities of breast cancer cells, and set out to rescue the expression of WT-EZH2 and the phospho-deficient T367A-EZH2 mutant in MDA-MB-231, -468, and SUM159 cells with EZH2 3′UTR knockdown." (PMID 30022044, 2018). "Therefore, we performed an immunohistochemistry-based evaluation of EZH2 expression in normal breast tissue in women with biopsy-confirmed benign breast disease (BBD) in the Nurses’ Health Studies and examined the association between EZH2 expression and subsequent breast cancer risk." (PMID 28253895, 2017). "When evaluating breast cancer risk by 5% increase in EZH2 expression and adjusting for matching factors between cases and controls, there was a significant increase in risk associated with EZH2 expression in epithelium (OR = 1.17, 95% CI = 1.03–1.34, p value = 0.021)." (PMID 28253895, 2017).
breast cancer (continued). "Consistent with our findings in the tissue microarray analysis that the presence of EZH2 in osteosarcoma is linked to higher metastatic migration, similar observations have also been reported in pancreatic cancer, prostate cancer, oral tongue squamous cell carcinoma, and breast cancer." (PMID 27223261, 2016). "Similarly, inhibition of EZH2, a histone H3 Lys27 (H2K27) methyltransferase and polycomb group protein, is associated with up-regulation of ERα in breast cancer cells, suggesting that targeting of EZH2 provides an option for restoring response to tamoxifen in endocrine-resistant breast cancers." (PMID 27884978, 2016). "Similarly, tissue microarray analysis of breast caner tissue samples showed EZH2 highly expressed in invasive breast cancer and metastatic breast cancer compared with normal or atypical hyperplasia, plus associated with breast cancer aggressiveness and poor clinical outcome." (PMID 25520914, 2014). "Furthermore, in both prostate and breast cancer, EZH2 expression was associated to more aggressive tumor subgroups, indicating that EZH2 expression may also serve as a novel prognostic marker." (PMID 20920340, 2010). "Thus, the determination of EZH2 expression may be an important new tool to identify patients at risk for developing breast cancer." (PMID 20920340, 2010). "Next, we determined whether EZH2 is also overexpressed in human BRCA1-deficient breast cancer." (PMID 19709408, 2009). "Consistent with the effects of crotonate, crotonyl-CoA also reduced EZH2 protein levels in multiple breast cancer cell lines." (PMID 41544165, 2026). "Short-chain fatty acid crotonate is a possible breast cancer killer through inducing the degradation of oncogenic protein EZH2." (PMID 41544165, 2026). "It indirectly increases the expression of EZH2 and encourages the invasion and metastasis of breast cancer cells." (PMID 41614928, 2026). "Here, we present a crotonate–crotonyl–coenzyme A (CoA)–enhancer of zeste homolog 2 (EZH2) crotonylation cascade blocking breast cancer growth and metastasis." (PMID 41544165, 2026). "Results demonstrated that overexpression of ACSS2 notably decreased EZH2 levels in breast cancer cells, whereas ACSS2 knockdown resulted in a marked increase in EZH2 levels." (PMID 41544165, 2026). "Together, these findings demonstrate the critical role of USP30-AS1 in breast cancer progression through HnRNPF/p21 and EZH2/c-Myc/p21 axes, highlighting its potential as a therapeutic target for breast cancer treatment." (PMID 41492473, 2026). "Together, our findings indicate that crotonate is a promising anticancer drug candidate that suppresses breast cancer growth and metastasis by specifically inducing EZH2 degradation." (PMID 41544165, 2026). "Our data demonstrated that USP30-AS1 plays an oncogenic function in breast cancer through HnRNPF/p21 and EZH2/c-Myc/p21 axes." (PMID 41492473, 2026). "Dysregulation of EZH2 frequently occurs in various cancers, making targeting EZH2 a promising therapeutic strategy for breast cancer treatment." (PMID 41544165, 2026). "EZH2 is localized in the nucleus of breast cancer cells and plays a crucial role in modulating the tumor microenvironment and regulating the cell cycle." (PMID 41607539, 2026). "To further confirm the association between crotonate and EZH2-mediated H3K27me3 regulation, we examined the expression levels of ACSS2, EZH2, and H3K27me3 in breast cancer and adjacent normal tissues using immunofluorescence." (PMID 41544165, 2026). "In comparison, crotonate showed better blocking effect than EZH2 inhibitor tazemetostat in suppressing breast cancer metastasis." (PMID 41544165, 2026). "Further, inhibition of EZH2 in vitro resulted in increased expression of ER in HER2+ human breast cancer cell lines and conferred sensitivity to Tamoxifen." (PMID 41606266, 2026). "Pharmacological targeting of EZH2 in combination with DOX represents a rational strategy to overcome chemoresistance in breast cancer." (PMID 42222149, 2026).
breast cancer (continued). "Correspondingly, EZH2 inhibitors exhibit some efficacy against Icosl-KO breast cancer, although this effect is weaker compared to that observed in wild-type breast cancer." (PMID 40708008, 2025). "Overexpression of EZH2 has been reported in various cancers, including breast cancer, esophageal cancer, poorly differentiated and anaplastic thyroid cancer, and several neuroendocrine cancers, where it seems to harbor an adverse prognosis." (PMID 40075585, 2025). "To exclude the system interference in HP5008 cells, we conducted CRISPR-Cas9 knockouts of Rad51b, Ezh2, Suz12 and Aebp2 in Brca1-mutant 545 cells, which were isolated from a primary mammary tumor of a Brca1-MSK mouse." (PMID 41318657, 2025). "In breast cancer, phosphorylation of EZH2 at T416 by cyclin-dependent kinase 2 is sufficient to promote tumor metastasis." (PMID 40028035, 2025). "To determine if DEK and EZH2 expression correlate in other models, we quantified their expression in breast cancer datasets." (PMID 40562540, 2025). "IHMT-337 covalently binds to EZH2 and degrades it through a ubiquitin-dependent pathway, thereby inhibiting the proliferation of breast cancer and diffuse large B-cell lymphoma." (PMID 40032852, 2025). "Our previous study reported the upregulation and oncogenic role of USP30-AS1 in breast cancer via the HnRNPF/p21 and EZH2/c-Myc/p21 axes." (PMID 41614739, 2025). "Among them, the HGF/c-MET pathway is closely related to cancer metastasis and can promote breast cancer resistance to tamoxifen through the EZH2/HOTAIR-MIR-141/200A feedback signaling pathway." (PMID 40860340, 2025). "Previous studies have shown that EZH2 is overexpressed in many solid cancers, including breast cancer, lung cancer, ovarian cancer and colon cancer, and is linked to cancer proliferation and aggressiveness." (PMID 40308579, 2025). "In breast cancer, EZH2 is now an important marker of aggressive behavior, with strong evidence for transcriptional repression and neoplastic transformation in cell-line studies, and higher expression in metastatic lesions than in primary lesions." (PMID 40075585, 2025). "Protein arginine methyltransferase facilitates breast cancer metastasis through EZH2 post-translational modifications." (PMID 40042761, 2025). "Recently, an epigenetic therapeutic drug targeting the histone methyltransferase EZH2 has also shown certain potential in the treatment of breast cancer." (PMID 40978031, 2025). "In the targeted treatment of breast cancer, EZH2-mediated silencing of protein phosphatase 2 regulatory subunit B leads to drug tolerance and acquired resistance to anti-human epidermal growth factor receptor 2 therapy." (PMID 40028035, 2025). "While the interaction between E2F1 and EZH2 in the activation of oncogenic pathways has been observed in other cancers, their collaborative role in breast cancer, especially in TNBC, remains largely unexplored." (PMID 41413688, 2025). "In breast cancer, the crucial histone methyl transferase EZH2 is frequently amplified and overexpressed." (PMID 40006021, 2025). "The previous published literature has shown positive therapeutic impact on various malignancies in the use of EZH2 inhibitors when they were combined with other chemotherapeutic drugs; for instance, in prostate, lung, ovarian, and breast cancer." (PMID 41614754, 2025). "Mutations in EZH2, particularly gain-of-function (GOF) mutations, have been identified in a variety of malignancies, including lymphomas, breast cancer, and prostate cancer, and frequently occur in the EZH2 SET domain." (PMID 40562788, 2025). "The result suggests that EZH2 expression is significantly higher in breast cancer tissues compared to normal breast tissues, with the highest levels observed in more aggressive subtypes like TNBC." (PMID 40038276, 2025). "Paclitaxel-resistant breast cancer cell lines had increased EZH2, ADAM10, ADAM17, and ICOSL expression, suggesting high sICOSL-release ability." (PMID 40708008, 2025).